Y_RNA (Y RNA )
Gene: Miscellaneous RNA gene on chromosome 10 (100,398,352 to 100,398,446, reverse strand). Ensembl gene ENSG00000212325.
Homologues: Orthologues: chimpanzee Y_RNA (99% identical), guinea pig Y_RNA (76% identical). Paralogues in human: RNY4 (89% identical), RNY4P6 (88% identical), RNY4P19 (87% identical), Y_RNA (87% identical), RNY4P13 (86% identical), RNY4P3 (86% identical), RNY4P7 (86% identical), Y_RNA (86% identical), RNY4P10 (85% identical), RNY4P24 (85% identical), Y_RNA (85% identical), RNY4P14 (84% identical), and 93 more.